CCND1 (cyclin D1)
Diseases named in the same sentence as CCND1 in open-access papers (continued):
Sharing a sentence is not in itself a finding about the gene and the disease.
tumor (continued). "Finally cyclin D1 levels do not decline during S phase in many tumor cells, so that only studies of normal cell types can with certainty be used to analyze cyclin D1 expression through the cell cycle." (PMID 17176475, 2006). "Third, cyclin D1b retains the ability of full-length cyclin D1 to modulate the action of some (but not all) transcription factors, and this differential function may hold consequence in selected tumor types." (PMID 16863592, 2006). "However, Myc-and Wnt1-induced neoplasms are independent of cyclin D1, whereas Hras-and Neu-induced carcinomas are dependent on cyclin D1, indicating that tumor phenotype and tumor genotype are not consistently matched." (PMID 15535849, 2004). "In agreement with this hypothesis, the three 11q13-amplified tumours with CCND1 normal expression were oestrogen receptor-negative." (PMID 11870541, 2002). "However, it should be noted that we also observed one oestrogen receptor-negative tumour with CCND1 overexpression and amplification (Tumour CCND1209)." (PMID 11870541, 2002). "The expressions of cyclin D1, cyclin E, cyclin-dependent kinase 4 (CDK4), and CDK2 were immunohistochemically examined in 90 patients with human oesophageal squamous cell carcinoma (SCC) to determine their relationship to the tumour behaviour and patient prognosis." (PMID 10390005, 1999). "The tumor cell subsets stratified by three main types: First, tumor-dominant cell subsets (Tumor 1 and 2 clusters) lacking clear enrichment of other cell types, with Tumor 1 cluster characterized by greater expression of proliferation genes (e.g., Ccnd1, Top2a, Myc)." (PMID 40171265, 2025). "Additionally, the immunohistochemical analysis indicated reduced expression of Ki67, MMP9, Cyclin D1, and CDK4 in the tumor tissues of CMHE-treated mice, implying the repression of the proliferative and metastatic ability of cancer cells in the tumor tissues by CMHE treatment." (PMID 39161904, 2024). "However, whether the tumor-suppressor gene LOC339059 promotes the differentiation of cancer cells still requires more experiments to validate its effect on the molecular differentiation markers b-catenin, CD44, and Cyclin D1." (PMID 38001573, 2023). "To test this hypothesis, we measured the expression levels of cyclin D1 (CCND1), one of the key regulators of the G1 to S phase transition.Protein levels of CCND1 were significantly lower in the TCF12 KO tumor cells compared to control and scramble tumor cells." (PMID 37046694, 2023). "Moreover, as the dysfunction of cyclin D1 E3 ligases is involved in desensitizing of cancer cells towards CDK4/6is in clinical practice, we utilized MG53 in combination with palbociclib and successfully enhanced the sensitivity of cancer cells to palbociclib and further repressed tumor growth." (PMID 37414783, 2023). "Additionally, nuclear cyclin D1 expression in GCs has been identified as an independent risk factor of GC tumour of the bone-recurrence after surgical therapy, as tumours displaying this trait have been known to be two times more recurrent than cyclin D1-negative tumours." (PMID 37509363, 2023). "In addition, the targets Cyclin D1 and Myc promote proliferation; in solid tumors an influence of Stat3 on VEGF expression could also further promote tumor growth and metastasis/tissue invasion through increased angiogenesis, a process of lower relevance for blood cancers." (PMID 36376859, 2022).
tumor (continued). "Additionally, Wnt-1, β-catenin, cyclin-D1, MMP2, and MMP9 as well as Ki-67 levels were higher in tumor cells of the model + sh-SOST group than that of the model + sh-NC group, demonstrating that SOST suppression was capable of activating Wnt/β-catenin signaling in ocular orthotopic tumor models." (PMID 35785219, 2022). "We speculate that CCND1 gene amplification activates metabolism signaling pathways, such as the enhanced oxidative metabolism in cancer cells promotes activation of PI3K-Akt-mTOR signal axis, and then constructs an immune barrier of tumor microenvironment, resulting in resistance to ICIs therapies." (PMID 35844619, 2022). "Except p21 and cyclin D1, several members of the PI3K/AKT pathway are significantly differentially expressed after MBNL2 depletion, hence, MBNL2 may regulate DNA damage response and tumor cell proliferation through other unknown mechanisms, which needs further investigation." (PMID 33466733, 2021). "In gene expression analysis, CCND1-amplified luminal A tumours showed increased proliferation (P < 0.001) and decreased progesterone (P = 0.002) levels along with a large overlap in differentially expressed genes when comparing luminal A and B-amplified vs. non-amplified tumours." (PMID 30819233, 2019). "However, forced expression of BCL2 or CCND1 alone does not suffice for in vivo tumour formation." (PMID 30451834, 2018). "However, Ccnd1-CAAX expression did not alter proliferative rates of tumor cells." (PMID 27105504, 2016). "In addition, other CDK-dependent or -independent non-canonical roles of cyclin D1 may be important for tumor initiation, maintenance, progression, and metastasis." (PMID 27286258, 2016). "However, in the absence of UBE2D3, cyclin D1 is not degraded and tumor cells continue to cycle." (PMID 25789002, 2015). "In addition to inhibition of apoptosis, activated NF-κB may control cell cycle progression by regulating the expression of important cell cycle regulatory proteins such as cyclin D1 and cyclin dependent kinase 2 (CDK2), further contributing to the tumour growth." (PMID 24416253, 2014). "Tumor inhibition may thus be induced by down-regulation of positive cell cycle regulators, such as cyclin D1, D2 and CDK4, along with up-regulation of the negative regulator, cyclin dependent kinase inhibitor, p27, and its subsequent inhibition of Rb phosphorylation and G1 arrest." (PMID 24040358, 2013). "Indeed, several studies have supported the notion that the oncogenic effects of cyclin D1 may not be simply due to enhanced tumor cell growth or proliferation." (PMID 23786849, 2013). "Therefore, in this case, a primary biopsy specimen taken from a limited location within the tumor may not accurately represent the extent of cyclin D1 staining." (PMID 23420289, 2013). "However, 70% of tumours with nuclear localisation of CTNNB1 did not display CCND1 overexpression." (PMID 19293793, 2009). "The expression of Ebp1, AR, Cyclin D1, ErbB3 and Ki67 were evaluated by immunohistochemistry using three separate tissue micro-arrays containing normal prostate tissues, non-cancerous tissue adjacent to the primary tumor, hormone-sensitive and hormone-refractory cancerous tissues." (PMID 19025630, 2008). "Interestingly, Cyclin D1 expression was detected in only 19% (3/16) of the GISTs with metastases (stomach 1, duodenum 2), but in 62% (8/13) of GISTs without metastases from various tumor sites (stomach 3, duodenum 3, ileum 1, colon 1)." (PMID 18651966, 2008). "More sensitive tumours may not require such high drug levels and it is unclear whether this discrepancy in drug exposure was responsible for the failure to demonstrate an effect on RB phosphorylation and cyclin D1 in peripheral blood mononuclear cells." (PMID 17179992, 2007). "However, three of the 15 11q13-amplified tumours were examined had not CCND1 overexpression." (PMID 11870541, 2002).
tumor (continued). "Moreover, overexpression of cyclin D1 alone may also contribute to tumour progression independent of CDK4 overexpression." (PMID 10390005, 1999). "The tumor was positive for CD99, SATB2, TLE1, cyclin D1, and focal FLI1, while negative for EMA, S100, desmin, calponin, and SOX10." (PMID 41869091, 2026). "Tumor cells were reactive to SMA, cluster of differentiation 34 (CD34) (focally), transducin-like enhancer of split-1 (TLE-1) (focally), and cyclin D1, with nuclear staining of beta-catenin, while it was not reactive to cytokeratins." (PMID 41246587, 2025). "In our case, the tumor showed strong and diffuse immunoreactivity for WT1 and CD10, with absent cyclin D1 expression." (PMID 41464215, 2025). "Immunohistochemical analysis showed the positivity of the tumor to CD20, CD5, Bcl2, and cyclin D1, while it was negative to CD10 and CD23." (PMID 38698463, 2024). "Histologically, the nodal tumor was largely diffuse with neoplastic small atypical lymphocytes co-expressing CD5, CD10, and CD20, but not CD23 or cyclin D1." (PMID 38535060, 2024). "Some noticeable genes with SVs were EGFR (three tumors in HPV positive and one tumor in HPV negative group), CCND1 (three tumors in each group), and PTEN (one in each group)." (PMID 38898085, 2024). "Similarly, in this work, no decrease in Cyclin D1 was observed in the tissues with any of the treatments used in this model, this leads to the assumption that the effect observed in the inhibition of tumor development was provided by another route other than the inhibition of Cyclin D1." (PMID 37960113, 2023). "CCND1b, but not CCND1, was sufficient to drive the transformation of NIH3T3 cells in vitro and tumour formation in vivo." (PMID 37510349, 2023). "In contrast, cyclin D1 and CD10 were negative, implying that the tumor did not originate from endometrial stromal cells." (PMID 36324740, 2022). "Reversible inhibition of ATP production and durable suppression of PTC growth indicates that the downregulation of mitochondrial function has a negative impact on tumor progression and LNM via the PI3K/Akt/FoxO1/Cyclin D1 pathway." (PMID 35865479, 2022). "We found that in tumor tissues with circ_0017109 knockdown, FZD4, β-catenin and non-phospho β-catenin, cyclin D1, and c-Myc showed significant reduction, and a higher level of cleaved caspase-3 and a lower level of Bcl-2 were also detected." (PMID 36434577, 2022). "Altogether, our results indicate that in obese mice bearing HCC, loss of PI3Kγ activity does not affect apoptosis or AKT phosphorylation in tumours but reduces ERK signalling, cyclin D1 expression, and tumour cell proliferation." (PMID 34704005, 2021). "In an in vitro cell model or in vivo tumor tissues, dipyridamole treatment resulted in a decline in the levels of HMGB1, RAGE, β-catenin, Runx2, YAP1, phosphorylated Smad2/3, and cyclin D1, but not TLR2 and TLR4." (PMID 33669632, 2021). "We have previously generated a genes signature induced by EGFR nuclear non-canonical activity, including two genes, TYMS and CCND1, upregulated by 5FU/CDDP chemotherapy in tumor cells." (PMID 33015030, 2020). "Importantly, the miR‐302e‐induced tumor suppressive effect could be effectively reversed by circ‐CMPK1 or cyclin D1 overexpression both in vitro and in vivo, implying that the ceRNA regulatory network of circ‐CMPK1/miR‐302e/cyclin D1 is objectively present and plays an important role in NSCLC." (PMID 31863641, 2020). "The lack of c‐MYC/8q24 rearrangements, as well as cyclin D1 and MYC expression in the tumor cells allowed for a diagnosis of DLBCL." (PMID 32100426, 2020).
tumor (continued). "Immunohistochemical staining of xenograft tumor tissues indicated that tumor tissues from mice in the si-circXPO1 group contained fewer CTNNB1- and cyclin D1-positive cells than those from mice in the negative control group." (PMID 33268793, 2020). "Upon treatment of these tumours with anti-RSPO3 antibody using patient-derived xenograft models, expression of LGR5 and ASCL2 were highly downregulated, whereas MYC, AXIN2 and CCND1 (cyclin D1) did not rank among the top 100 downregulated genes." (PMID 30792270, 2019). "Tumor cells are positive for CD20 and CD79a or abnormal expression of CD43, and negative for CD5, CD10 and Cyclin D1." (PMID 29489937, 2018). "Even more surprising was the absence of cyclin D1 in exosomes produced by PCI-13 and PC-30 cells, even though this protein was very strongly expressed in the parental tumor cells." (PMID 30370252, 2018). "IHC was mainly positive for tumor markers like CD10, CD20, CD45, CD 79a, PAX5, MUM1, and BCL6, and negative for BCL2, ALK, CD30, and cyclin D1." (PMID 30764662, 2018). "Our data revealed a significant negative correlation between CCND1 expression and miR-503 expression in ESCC tumor samples (P < 0.001, r = −0.523, Pearson)." (PMID 28602785, 2017). "Cyclin D1 has a heterogeneous subcellular distribution in MCL cell lines and primary tumour cells, but its presence in the cytoplasm does not mean that it is excluded from the nucleus." (PMID 29066743, 2017). "Subsequently, treatment with stERAP-6 every 4 days also significantly suppressed E2-induced expression of TFF1 and CCND1 and phosphorylation levels of Akt and MAPK in tumours, but treatment with unstapled original ERAP did not." (PMID 28500289, 2017). "The basal/SCC‐like cases in the same consensus cluster showed almost no expression of FGFR3 and CCND1, whereas the reverse was seen for KRT5 and CDH3 tumour‐cell expression." (PMID 28195647, 2017). "The dependency upon Cyclin D1, MASTL and COPZ1 activity is restricted to tumor cells and not normal thyroid cells, as previously reported for other tumor types." (PMID 26431489, 2015). "Consistently, the transcription of WNT5A and CCND2, but not CCND1, was also elevated in PIAS1 knockdown xenograft tumor samples." (PMID 24586797, 2014). "The primary tumor cells were positive for bcl-2, CD20, CD43, CD79a, Lambda, Kappa and was negative for CD10, IgG, IgG4, IgM, cyclin D1, bcl-6, CK (AE1/3), and Helicobacter pylori (data not shown)." (PMID 21892966, 2011). "The recurrent tumor showed negativity for CD10, IgG, IgG4, IgM, cyclin D1, Bcl-6, CK (AE1/3), and Helicobacter pylori (data not shown) except that the recurrent tumor showed negativity for lambda and weak positivity for kappa." (PMID 21892966, 2011). "All five samples studied were cyclin-D1 positive: however, its expression was not as strong as that of CCHCR1 and more concentrated to the centre of the tumor nests (data not shown)." (PMID 19551138, 2009). "In a univariate analysis, the prognosis of patients with tumours that were both cyclin D1- and CDK4-positive was significantly poorer than that of patients with cyclin D1-negative tumours (P < 0.05)." (PMID 10390005, 1999). "Tumor cells typically express CD20, CD5, and Cyclin D1, while lacking CD10 and Bcl-6." (PMID 41585338, 2026). "By IHC, the tumor cells were positive for CD10, and the tumor cells were negative for Cyclin D1." (PMID 39469368, 2024). "In this study, we identified a subset (8.3%) of CRC patients who, irrespective of tumor metastasis, have a poorer prognosis due to their tumor tissues exhibiting high TCF12 mRNA, high MALAT1, low β-catenin mRNA, and high cyclin D1 mRNA levels, referred to as the TMBC pattern." (PMID 39768127, 2024).
tumor (continued). "However, while this was the case in one of the tumor lines, HCC1806, the other three either showed no change (DMS 53 and RT4) or, conversely, induced an up-regulation of Cyclin D1 (5637)." (PMID 38386805, 2024). "In our study, we discovered that 8.3% of CRC patients, regardless of whether they experience tumor metastasis, have poor prognosis due to their tumor tissues expressing high TCF12 mRNA, high MALAT1, low β-catenin mRNA, and high cyclin D1 mRNA." (PMID 39768127, 2024). "In addition, the tumor cells were positive for BCL-6 (G/191E/A8) andCD10 (SP67, Ventana) and negative for Cyclin D1 (SP4-R, Ventana) and MUM-1 (MUM1p, Dako)." (PMID 37202787, 2023). "To validate the results obtained in our in vitro experiments, we tested the anti-tumour activity of AZD1775, neratinib or everolimus in the presence or absence of Fulv in an in vivo PDX model of metastatic ER + CCND1-driven BC with acquired resistance to palbociclib (HBCx-134 palbo-R31)." (PMID 32307447, 2020). "Moreover, in tumor tissue by uninterrupted slicing and IHC assay we found that an obvious positive correlationbetween ASPM and CDK4 but not CCND1 (data not shown) was existed." (PMID 32742488, 2020). "It is expected that tumor cells without LOH for hDMP1 and Cyclin D1, low express high hDMP1." (PMID 33120969, 2020). "Interestingly, when cyclin D1 was silenced the TTP was significantly prolonged (p < 0.05) with respect to controls and RT resulted in no tumor progression in both xenograft models." (PMID 26689991, 2016). "Although preferential positioning of CCND1 and HER-2/neu sequences at the periphery of the CTs has been observed in two types of tumor, our data did not reveal a relationship between gene positioning and the amplification and over-expression status of these genes." (PMID 21637674, 2009). "Because none of the tumor samples analyzed by CGH were assessed as being CCND1 amplified by FISH, the CCND1 amplification status between these two methods could not be compared." (PMID 18823530, 2008). "Altogether, this discovery, along with the low FARSA levels in MCL patients as well as the negative correlation between FARSA and CCND1, suggests that FARSA may serve as a tumor suppressor in MCL, and low FARSA levels may confer chemoresistant properties to MCL cells." (PMID 36675119, 2023). "In addition, Oxy186, but not Oxy210, also inhibits A549 xenograft tumor growth in vivo, and RNA-seq analysis of Oxy186-treated xenograft tumor samples confirmed the inhibition of WNT target gene expression, including MYC and Cyclin D1 (CCND1)." (PMID 35908024, 2022). "Immunohistochemistry and western blotting analyses showed reduced protein expression of CHI3L1, PCNA, cyclin D1, Cdk 6, and MMP‐9, but the expression of cleaved caspase‐3 was increased; however, IL‐13Rα1 and IL‐13Rα2 levels were not changed in K284‐treated lung metastasis tumor tissues." (PMID 34758182, 2022). "Notably, while bevacizumab treatment reduced the expression of Cyclin D1, GLUT-1 and MCT-1, TH reverted such effects, thus showing that VEGF-A is not the only TH-target gene in tumor promotion, and that VEGF-A is part of pro-tumorigenic cascade in the TH-dependent tumorigenic action." (PMID 34205977, 2021). "Indeed, all these data suggest that pharmacological inactivation of Cyclin D1/CDK could be included in the therapeutic portfolio, not only to counteract tumor cell proliferation but also against the invasive capacity." (PMID 33317149, 2020).